DMPK (DM1 protein kinase)
Diseases named in the same sentence as DMPK in open-access papers (continued):
Sharing a sentence is not in itself a finding about the gene and the disease.
myotonic dystrophy type 1 (continued). "We inferred neutral evolution for the three other microsatellites causative of the trinucleotide expansion disorders SCA3 (ATXN3), dentatorubral-pallidoluysian atrophy (DRPLA) (ATN1), and myotonic dystrophy type 1 (DM1) (DMPK)." (PMID 39775235, 2024). "Myotonic dystrophy type 1 (DM1) is a debilitating chronic disease caused by an expansion of the unstable CTG triplet repeat in the 3' untranslated region of the DM1 protein kinase (DMPK) gene." (PMID 36627397, 2023). "Myotonic dystrophy type 1 (DM1), the most common form of adult muscular dystrophy, is caused by an abnormal expansion of CTG repeats in the 3′ untranslated region of the dystrophia myotonica protein kinase (DMPK) gene." (PMID 36835205, 2023). "Myotonic Dystrophy type 1 (DM1, OMIM# 160900) is caused by an expanded CTG tract in the 3′ untranslated region (3′ UTR) of the dystrophia myotonica protein kinase (DMPK) gene that mainly affects muscular and neuronal lineages." (PMID 35019138, 2022). "Myotonic dystrophy type 1 (DM1), one of the most common forms of adult-onset muscular dystrophy, is caused by abnormally expanded CTG repeats in the 3′ untranslated region of the DMPK gene." (PMID 36510245, 2022). "For comparison, RNA toxicity has been described for myotonic dystrophy type 1 (DM1), a disease caused by a CTG expansion in the 3′unstranslated region of the DMPK gene." (PMID 36675972, 2022). "Myotonic dystrophy type 1 (DM1) is an autosomal dominant muscular dystrophy that results from a CTG expansion (50–4000 copies) in the 3′ UTR of the DMPK gene." (PMID 34776509, 2022). "Second, patient 1, described elsewhere, had an asymptomatic genetic background of myotonic dystrophy type 1 (DM1) with expanded CTG repeats in the DMPK gene, in addition to I536T-RBM20." (PMID 36198914, 2022). "Long CTG repeats have been identified in the DMPK gene of patients of Myotonic Dystrophy type 1 (DM1), although the healthy person has the CTG repeat within the range of 5–38." (PMID 33431896, 2021). "The first reported RNA foci were in Myotonic dystrophy type 1 (DM1) patients, which is caused by a CTG repeat expansion of the DMPK gene and is a typical RNA toxicity disease." (PMID 32983232, 2020). "Myotonic dystrophy type 1 (DM1) is an inherited neuromuscular disease which results from an expansion of repetitive DNA elements within the 3' untranslated region of the DMPK gene." (PMID 32155193, 2020). "Myotonic dystrophy type 1 (DM1) is a slowly progressive inherited multisystem disorder, caused by the expansion of an unstable CTG trinucleotide repeat in the DMPK gene on chromosome 19q13.3." (PMID 30922263, 2019). "Myotonic dystrophy type 1 (DM1, “Steinert's disease”) is caused by an unstable trinucleotide (CTG) repeat expansion in the 3′-UTR of the dystrophia myotonica-protein kinase (DMPK) gene." (PMID 31681146, 2019). "Myotonic dystrophy type 1 (DM1) and its severe congenital form (CDM1) are caused by an expansion of CTG repeats in the 3′-untranslated region (UTR) of the DMPK gene." (PMID 29789616, 2018). "Myotonic dystrophy type 1 (DM1) is a multisystemic disorder with predominant myotonia and muscular dystrophy which is caused by CTG-repeat expansions in the DMPK gene." (PMID 30425655, 2018). "Myotonic dystrophy type 1 (DM1) originates from a progressive expansion of CTG repeats in the 3’-unstranslated region of the dystrophia myotonica protein kinase (DMPK) gene." (PMID 28582438, 2017). "The second MD described, myotonic dystrophy type 1 (DM1), is a neuromuscular disorder caused by a microsatellite CTG repeat expansion in the 3'UTR of the dystrophia myotonica protein kinase (DMPK) gene." (PMID 25859781, 2015). "In contrast, the CTG repeat expansion responsible for myotonic dystrophy type 1 (DM1), a multi-systemic disease affecting mainly the muscle but also the brain, is located in the 3′-untranslated region of the DMPK gene." (PMID 19680445, 2009).
myotonic dystrophy type 1 (continued). "Conversely, UTR and intronic loci, such as DMPK and NOP56 (myotonic dystrophy type 1 and spinocerebellar ataxia 36), have higher genotyping rates across all exome capture kits analysed." (PMID 40004498, 2025). "CELF1 has been reported to play a role in myotonic dystrophy type 1 (DM1), a type of muscular dystrophy in humans, via interactions with the dystrophia myotonica-protein kinase (DMPK) gene." (PMID 39858630, 2025). "In myotonic dystrophy type 1, the length of CTG repeats in the DMPK gene exceeding 35 repeats tends to be unstable and can expand in length during gametogenesis." (PMID 39643839, 2025). "Similarly, in myotonic dystrophy type 1 (DM1) it has been shown that individual-specific residual variation in DMPK CAG•CTG repeat somatic expansion (after correcting for allele length and age) was correlated across blood, skin and skeletal muscle DNA." (PMID 39375222, 2024). "An illustrative example of the application of text mining in biomedical research is myotonic dystrophy type 1 (DM1), an autosomal dominant genetic disease caused by the abnormal expansion of unstable CTG repeats in the 3’ untranslated region of the myotonic dystrophy protein kinase (DMPK) gene." (PMID 39311198, 2024). "Myotonic dystrophy type 1 (DM-1) is a progressive multisystem genetic disorder that causes myotonia and both distal limb and facial/neck muscle weakness by expanding the CTG repeats of the DMPK gene in chromosome 19q13.3." (PMID 38050269, 2023). "Myotonic dystrophy type 1 (DM1) is one of the most common muscular dystrophies and can be potentially treated with antisense therapy decreasing mutant DMPK, targeting miRNAs or their binding sites or via a blocking mechanism for MBNL1 displacement from the repeats." (PMID 36769018, 2023). "Myotonic dystrophy type 1 (DM1) is a dominant genetic disease in which the expansion of long CTG trinucleotides in the 3′ UTR of the myotonic dystrophy protein kinase (DMPK) gene results in toxic RNA gain-of-function and gene mis-splicing affecting mainly the muscles, the heart, and the brain." (PMID 36362145, 2022). "Chloroquine (CQ), an inhibitor of autophagosome-lysosome fusion, is proposed for the treatment of myotonic dystrophy type 1 (DM1), a debilitating neuromuscular disease caused by the expansion of a CUG repeat in the 3′ UTR of the DMPK (DM1 protein kinase) pre-mRNA." (PMID 35585060, 2022). "In myotonic dystrophy type 1 and 2 (DM1 and DM2), for example, mutations in the DMPK and ZNF9/CNBP genes, respectively, disrupt the alternative splicing of the CLCN1 gene, creating a secondary reduction in sarcolemmal ClC-1 protein expression and current density." (PMID 32117034, 2020). "Myotonic dystrophy type 1 (DM-1), or Steinert disease, is a genetic disease due to an expansion of CTG triplet in DMPK gene on chromosome 19." (PMID 30393639, 2018). "CELF1 gene may have a role in myotonic dystrophy type 1 (DM1) because of its interactions with the dystrophia myotonica-protein kinase (DMPK) gene." (PMID 29056900, 2017). "The CELF1 gene may play a role in myotonic dystrophy type 1 (DM1) via interactions with the dystrophia myotonica-protein kinase (DMPK) gene." (PMID 24237593, 2013). "We also included PPP2R2B and DMPK, expansions of CAG•CTG repeats within which underlie spinocerebellar ataxia type 12 (SCA12, MIM #604326) and myotonic dystrophy type 1 (DM1, MIM #160900), respectively, but are not translated into polyglutamine." (PMID 38449714, 2024). "Myotonic dystrophy type 1 [DM1, (OMIM 160900)] is an autosomal dominant muscular dystrophy that results from a trinucleotide CTG repeat expansion (50–4000 copies) in the 3′ UTR of the dystrophia myotonica protein kinase gene (DMPK)." (PMID 34776509, 2022). "Myotonic dystrophy type 1 (DM1, OMIM#160900) is an autosomal dominant muscular dystrophy that results from a trinucleotide CTG repeat expansion (50–>3000 triplets) in the 3′-UTR of the DMPK gene." (PMID 33921346, 2021).
myotonic dystrophy type 1 (continued). "For example, in myotonic dystrophy type 1 (DM1), an expanded CUG repeat (CUGexp) in the 3′ UTR of the DM Protein Kinase (DMPK) transcript disrupts splicing regulator proteins in the muscleblind-like (MBNL) family, causing abnormal splicing of a number of pre-mRNAs2,3." (PMID 30254196, 2018). "RNA toxicity from CTG trinucleotide repeat (TNR) expansion within noncoding DNA of the transcription factor 4 (TCF4) and DM1 protein kinase (DMPK) genes has been described in Fuchs' endothelial corneal dystrophy (FECD) and myotonic dystrophy, type 1 (DM1), respectively." (PMID 30025114, 2018). "For example, in the neuromuscular disorder Myotonic Dystrophy Type 1 (DM1), an expansion of CTG repeats in the 3'UTR of the Dystrophia Myotonica Protein Kinase (DMPK) gene results in retention of CUG-containing DMPK mRNAs within specific RNA foci in the nucleus." (PMID 26824521, 2016). "Moreover, induction of autophagy and inhibition of the mTOR pathway have been found in human myoblasts of myotonic dystrophy type 1 (DM1), a noncoding repeat expansion RNA toxicity diseases due to gain-of-function effect of the RNA of the DMPK gene." (PMID 23626835, 2013). "Myotonic dystrophy type 1 (DM1) is a progressive, dominantly inherited, multisystem disease caused by an expanded and unstable trinucleotide CTG repeat localized to the 3' untranslated region of the dystrophia myotonica protein kinase (DMPK) gene on chromosome 19q13.3." (PMID 20482818, 2010). "In particular, in myotonic dystrophy type 1 (DM1), extensive AS changes result from the CUG expansions in the DMPK gene characterizing the disease." (PMID 33757121, 2022). "It was recently suggested that circular RNAs expression can be affected by splicing alterations related to myotonic dystrophy type 1 (DM1), a multisystemic disorder in which expanded CTG repeats in the DMPK gene leads to splicing abnormalities." (PMID 32117954, 2019). "Myotonic dystrophy type 1 (DM1) is a dominantly inherited, multisystem disorder, resulting from expansion of a CTG trinucleotide repeat in the 3’-untranslated region of DMPK." (PMID 31306140, 2019). "The disorder encompasses two genetically distinct types: myotonic dystrophy type 1 (DM1, OMIM 160900) and myotonic dystrophy type 2 (DM2, OMIM 602668), attributable to CTG expansion in 3’UTR of the DMPK gene and CCTG repeats in the first intron of the CNBP gene, respectively." (PMID 40133672, 2025). "Myotonic dystrophy type 1 (DM1) is the most common form of adult muscular dystrophy and results from a CTG repeat tract expansion in the 3′ untranslated region (3′UTR) of the dystrophia myotonica protein kinase (DMPK) gene." (PMID 39258536, 2024). "Myotonic dystrophy type 1 (DM1; Steinert’s disease, MIM#160900) is the most common muscular dystrophy in adulthood due to an unstable CTG expansion in the 3′ untranslated region of the myotonic dystrophy protein kinase (DMPK) gene (MIM#605377)." (PMID 36555146, 2022).
myotonic dystrophy (48 papers, 2008 to 2026). An inherited progressive disorder affecting the muscles. "The six individuals with DMPK-associated allele lengths longer than the known pathogenic cutoff were known to have been molecularly and clinically diagnosed with myotonic dystrophy (OMIM#160900), an autosomal dominant disorder." (PMID 36701310, 2023). "One patient was diagnosed after further testing, i.e., by analysis of the DMPK gene, associated with myotonic dystrophy, performed outside of the UMCG (a trinucleotide repeat as causal variant are not detected by ES)." (PMID 34136434, 2021). "Remarkably, FECD is also caused by the mutant CTG expanded repeat within the 3′-untranslated region of the DMPK gene that is also associated with myotonic dystrophy." (PMID 32463444, 2020). "A trinucleotide (CTG) repeat expansion in the 3′UTR of the myotonic dystrophy protein kinase (DMPK) gene causes myotonic dystrophy and disrupts the normal function of the CELF1 splicing factor." (PMID 33321981, 2020). "Myotonic dystrophies (DM) are slowly progressing multisystemic disorders caused by repeat expansions in the DMPK or CNBP genes." (PMID 30140252, 2018). "Myotonic dystrophy (DM) is a dominantly inherited neuromuscular disorder caused by expression of mutant myotonin-protein kinase (DMPK) transcripts containing expanded CUG repeats." (PMID 29592894, 2018). "DMPK is expressed in all major muscles including smooth, skeletal, and cardiac muscles and is linked to myotonic dystrophies." (PMID 28152551, 2017). "Nevertheless, our findings are consistent with a recent study, which suggested that DMPK is implicated in myotonic dystrophy by its dysregulation of MBNL1 and CELF1 mediated alternative splicing of the L-type calcium channel CACNA1S." (PMID 28152551, 2017). "Myotonic dystrophy (DM1) is caused by a (CTG)n repeat expansion in the 3′ UTR of the DMPK gene which results in nuclear retention of mutant DMPK transcripts in RNA foci." (PMID 24781112, 2014). "While Cugbp1 is not directly linked to the formation of cataracts, expansion of CTG repeats in the 3'UTR of the human DMPK gene cause myotonic dystrophy, a form of adult muscular dystrophy that is accompanied by cataract formation." (PMID 21896182, 2011). "DMPK-associated myotonic dystrophy (OMIM#160900) is among one of the best-studied STR loci." (PMID 36701310, 2023). "All repeat expansions existed in DMPK, a gene associated with myotonic dystrophy 1 in which “normal alleles” consist of 5–34 CTG repeats within the 3′ UTR, typically asymptomatic “premutation alleles” between 35 and 49, and fully penetrant alleles over 50 CTG repeats." (PMID 37745687, 2023). "This included a CTG expansion in myotonic dystrophy-linked DMPK we reported previously." (PMID 35546631, 2022). "DMPK is of particular interest because its expression is restricted to muscles, including smooth muscle, and is directly linked to muscular diseases such as myotonic dystrophy." (PMID 28152551, 2017). "Researchers identified both U2AF and PSF, as well as hnRNP C and PTB, as RNA-binding proteins that bind to two regions 3’ of the (CUG)n repeat expansion in the 3’-UTR of the DMPK gene, where expansion of this trinucleotide repeat causes the neuromuscular disorder myotonic dystrophy." (PMID 22682314, 2012). "Myotonic dystrophy is the most common MD in adult and is a complex multisystemic inherited muscle degenerative disorder caused by a pathogenic expansion of microsatellite repeats within noncoding elements of dystrophia myotonica protein kinase (DMPK) or zinc finger protein 9 (ZNF9) genes." (PMID 22761545, 2012). "Of those remaining, the largest number of calls with predicted expansions were the ones in DMPK (myotonic dystrophy), GLS (global developmental delay, progressive ataxia and elevated glutamine) and HTT (Huntington disease)." (PMID 40004498, 2025).
myotonic dystrophy (continued). "Postnatal microarray, Prader‐Willi methylation testing, DMPK analysis for myotonic dystrophy and Spinal Muscular Atrophy genetic testing were all unremarkable." (PMID 40445116, 2025). "In the unrelated primary schizophrenia cohort, we previously reported a > 200 repeat-long CTG expansion in DMPK, within the known pathological range, and consistent with a history of myotonic dystrophy in the individual’s family." (PMID 35546631, 2022). "Myotonic dystrophy (DM1), a neuromuscular disease related to DMPK gene mutations, is associated to endocrine disorders and cancer." (PMID 30760283, 2019). "To demonstrate the utility of AP-FRET in identifying RNA-protein interactions we first turned to the interaction of MBNL1 and DMPK RNA, which have been extensively studied in myotonic dystrophy." (PMID 24781112, 2014). "To address this, we utilized transgenic mice over-expressing the DMPK 3′ UTR as part of an inducible RNA transcript to model early-onset myotonic dystrophy." (PMID 24039817, 2013). "Other regions with this function were described in the myotonic dystrophy gene DMPK, in the ICR (Imprinted Control Region) of IGF2 and in the neighboring BLU and RASSF1A loci of the 3p21.3 gene cluster region." (PMID 23874213, 2013). "Myotonic dystrophy is recognized as an autosomal dominant disorder, with its pathogenesis linked to the expansion of a CTG trinucleotide repeat sequence within the untranslated 3′ region of the DMPK gene, resulting in abnormal protein kinase production." (PMID 41195013, 2025). "In addition to DM2, there is another form of myotonic dystrophy, DM type 1 (DM1, Steinert’ disease, MIM 160900), caused by an expansion of CTG repeats in the 3′ untranslated region of the DM protein kinase (DMPK) gene." (PMID 37762484, 2023). "In this context, reduced availability of the splicing factor MBNL1, due to the expression of expanded CUG or CCUG repeats in noncoding regions of the genes encoding the Myotonic Dystrophy Associated Protein Kinase (DMPK) and Zinc Finger Protein 9 (ZNF9), is responsible for Myotonic Dystrophy (DM)." (PMID 35269658, 2022). "DNA analysis for patient 2 for myotonic dystrophy (DMPK) was unremarkable." (PMID 34828389, 2021). "Importantly, polyalanine-ATXN8 proteins have been observed in the cerebella of SCA8 human patients and mouse models, and a similar approach has provided evidence of a polyglutamine RAN product from the DMPK gene with expanded CAG repeats in myotonic dystrophy." (PMID 32777047, 2020). "Myotonic dystrophy (DM1), one of the most common muscular dystrophies in adults, is an RNA-dominant disorder caused by the expression of expanded microsatellite repeats located in the 3′ untranslated region (UTR) of the DM1 protein kinase (DMPK) gene." (PMID 31479430, 2019). "By positional cloning, the DM1 mutation associated with type 1 myotonic dystrophy was identified as a variable length polymorphism which resulted from increased number of trinucleotide CUG repeats in the 3′UTR of DM protein kinase (DMPK) expressed in tissues affected by myotonic dystrophy." (PMID 26498036, 2015). "Myotonic dystrophy (DM) of type 1 and 2 (DM1 and DM2) are inherited autosomal dominant diseases caused by dynamic and unstable expanded microsatellite sequences (CTG and CCTG, respectively) in the non-coding regions of the genes DMPK and ZNF9, respectively." (PMID 24409116, 2014). "Additionally, DMPK (ENSG00000104936), a gene identified in our study, is known to be associated with myotonic dystrophy, a disease for which advanced paternal age is a risk factor." (PMID 25010591, 2014). "A mouse model which presents typical symptoms of myotonic dystrophy when a normal DMPK 3′UTR mRNA is over-expressed clearly raises issues as to the relative role of the expansion itself and of the non repeat DMPK 3′UTR in the pathogenicity of CUG expanded RNA in DM1 patients." (PMID 18213375, 2008).